ACE (angiotensin I converting enzyme)
Description:
Dipeptidyl carboxypeptidase that removes dipeptides from the C-terminus of a variety of circulating hormones, such as angiotensin I, bradykinin or enkephalins, thereby playing a key role in the regulation of blood pressure, electrolyte homeostasis or synaptic plasticity. Composed of two similar catalytic domains, each possessing a functional active site, with different selectivity for substrates. Plays a major role in the angiotensin-renin system that regulates blood pressure and sodium retention by the kidney by converting angiotensin I to angiotensin II, resulting in an increase of the vasoconstrictor activity of angiotensin. Also able to inactivate bradykinin, a potent vasodilator, and therefore enhance the blood pressure response. Acts as a regulator of synaptic transmission by mediating cleavage of neuropeptide hormones, such as substance P, neurotensin or enkephalins. Catalyzes degradation of different enkephalin neuropeptides (Met-enkephalin, Leu-enkephalin, Met-enkephalin-Arg-Phe and possibly Met-enkephalin-Arg-Gly-Leu). Acts as a regulator of synaptic plasticity in the nucleus accumbens of the brain by mediating cleavage of Met-enkephalin-Arg-Phe, a strong ligand of Mu-type opioid receptor OPRM1, into Met-enkephalin (By similarity). Met-enkephalin-Arg-Phe cleavage by ACE decreases activation of OPRM1, leading to long-term synaptic potentiation of glutamate release (By similarity). Also acts as a regulator of hematopoietic stem cell differentiation by mediating degradation of hemoregulatory peptide N-acetyl-SDKP (AcSDKP). Acts as a regulator of cannabinoid signaling pathway by mediating degradation of hemopressin, an antagonist peptide of the cannabinoid receptor CNR1. Involved in amyloid-beta metabolism by catalyzing degradation of Amyloid-beta protein 40 and Amyloid-beta protein 42 peptides, thereby preventing plaque formation. Catalyzes cleavage of cholecystokinin (maturation of Cholecystokinin-8 and Cholecystokinin-5) and Gonadoliberin-1 (both maturation and degradation) hormones. Degradation of hemoregulatory peptide N-acetyl-SDKP (AcSDKP) and amyloid-beta proteins is mediated by the N-terminal catalytic domain, while angiotensin I and cholecystokinin cleavage is mediated by the C-terminal catalytic region. [Angiotensin-converting enzyme, soluble form]: Soluble form that is released in blood plasma and other body fluids following proteolytic cleavage in the juxtamembrane stalk region. [Isoform Testis-specific]: Isoform produced by alternative promoter usage that is specifically expressed in spermatocytes and adult testis, and which is required for male fertility. In contrast to somatic isoforms, only contains one catalytic domain. Acts as a dipeptidyl carboxypeptidase that removes dipeptides from the C-terminus of substrates. The identity of substrates that are needed for male fertility is unknown (By similarity). May also have a glycosidase activity which releases GPI-anchored proteins from the membrane by cleaving the mannose linkage in the GPI moiety. The GPIase activity was reported to be essential for the egg-binding ability of the sperm (By similarity). This activity is however unclear and has been challenged by other groups, suggesting that it may be indirect (By similarity).
Synonyms: CD143; DCP; DCP1; ACE1
Tractability: Small molecule: an approved drug acts on it; a structure with a bound ligand is known; a high-quality ligand is known; it has a high-quality binding pocket; it belongs to a druggable protein family. Antibody: UniProt places it where antibodies can reach, with high confidence; its Gene Ontology location is reachable by antibodies, with high confidence; UniProt predicts a signal peptide or a membrane-spanning region. PROTAC: ubiquitination databases record sites on it; its protein half-life has been measured; a small molecule that binds it is known.
Target class: Protease; Metallo protease; Metallo protease M2 family; Enzyme; Metallo protease MAE clan
Safety:
Unwanted effects reported when the protein is acted on. In parentheses: how it was acted on, where the effect was seen, and who reports it.
decreased blood pressure (inhibition, acute dosing; renal, cardiovascular; source: Lynch et al. (2017))
decreased bone marrow erythropoiesis (inhibition, acute dosing; renal, cardiovascular; source: Lynch et al. (2017))
gastrointestinal hemorrhagic erosion/ulcer (inhibition, acute dosing; renal, cardiovascular; source: Lynch et al. (2017))
hepatocytic vacuolar degeneration (inhibition, acute dosing; renal, cardiovascular; source: Lynch et al. (2017))
increased risk spontaneous abortion (inhibition, developmental toxicity; renal, cardiovascular; source: Lynch et al. (2017))
increased urinary sodium excretion (inhibition, acute dosing; renal, cardiovascular; source: Lynch et al. (2017))
increased urine excretion (inhibition, acute dosing; renal, cardiovascular; source: Lynch et al. (2017))
interstitial cell infiltration (inhibition, acute dosing; renal, cardiovascular; source: Lynch et al. (2017))
juxtaglomerular cell hyperplasia (inhibition, acute dosing; renal, cardiovascular; source: Lynch et al. (2017))
proximal tubular degeneration (inhibition, acute dosing; renal, cardiovascular; source: Lynch et al. (2017))
aspirin intolerance (source: ClinPGx)
diabetes mellitus (source: ClinPGx)
major cardiovascular events or mortality (source: ClinPGx)
Gene: Protein-coding gene on chromosome 17 (63,477,058 to 63,498,380, forward strand). Ensembl gene ENSG00000159640.
Subcellular location: Cell membrane; Cytoplasm; Secreted (Angiotensin-converting enzyme, soluble form); Cell membrane (Isoform Testis-specific); Secreted
Subcellular location (Human Protein Atlas): Vesicles; Predicted to be secreted
Pathways (Reactome):
Metabolism of proteins: Metabolism of Angiotensinogen to Angiotensins
Gene Ontology:
Molecular function: bradykinin receptor binding; chloride ion binding; endopeptidase activity; exopeptidase activity; metallodipeptidase activity; metalloendopeptidase activity; metallopeptidase activity; mitogen-activated protein kinase binding; mitogen-activated protein kinase kinase binding; peptidase activity; peptidyl-dipeptidase activity; tripeptidyl-peptidase activity; zinc ion binding; metallocarboxypeptidase activity
Biological process: amyloid-beta metabolic process; angiotensin maturation; arachidonate secretion; bradykinin catabolic process; hormone catabolic process; hormone metabolic process; kidney development; peptide catabolic process; regulation of angiotensin metabolic process; regulation of systemic arterial blood pressure by renin-angiotensin; substance P catabolic process; angiotensin-activated signaling pathway; antigen processing and presentation of peptide antigen via MHC class I; blood vessel diameter maintenance; blood vessel remodeling; cell proliferation in bone marrow; heart contraction; hematopoietic stem cell differentiation; mononuclear cell proliferation; negative regulation of gap junction assembly; neutrophil mediated immunity; positive regulation of systemic arterial blood pressure; proteolysis; regulation of blood pressure; regulation of heart rate by cardiac conduction; and 9 more
Cellular component: endosome; external side of plasma membrane; extracellular exosome; extracellular region; lysosome; plasma membrane; cytoplasm; membrane
Genetic constraint (gnomAD): Loss-of-function variants: 125 observed, 164.73 expected, observed/expected ratio (o/e) 0.76, 90% interval 0.65 to 0.88. The upper end of that interval is the gene's LOEUF score, 0.88, which puts it in group 3 of 6, group 1 being the genes least tolerant of losing a copy. Missense variants: 1,776 observed, 1,718.9 expected, observed/expected ratio (o/e) 1.03, 90% interval 0.99 to 1.07. Synonymous variants: 786 observed, 704.3 expected, observed/expected ratio (o/e) 1.12, 90% interval 1.05 to 1.18.
Homologues: Orthologues: chimpanzee ACE (99% identical), macaque ACE (98% identical), guinea pig ACE (86% identical), pig ACE (85% identical), rat Ace (84% identical), mouse Ace (83% identical), rabbit ACE (80% identical), dog ACE (75% identical). Paralogues in human: ACE2 (21% identical).
Diseases named in the same sentence as ACE in open-access papers:
ACE is named in the same sentence as 975 diseases in open-access papers, as found by Europe PMC text mining. Sharing a sentence is not in itself a finding about the gene and the disease. The quoted sentences say what the papers report.
Hypertension (3,383 papers, 2002 to 2026). The presence of chronic increased pressure in the systemic arterial system. "The central role of the RAS in hypertension is further underscored by research showing that genetic variations in the ACE gene can interact to influence susceptibility to essential hypertension." (PMID 41331424, 2025). "Higher SBP was associated with histories of hypertension and/or chronic HF, outpatient use of ACE inhibitors, ARBs, or nitroglycerin, and higher BNP." (PMID 40877742, 2025). "In another in vitro study, it was proven that P. pulmonarius mycelium can enhance the anti-hypertensive activity by inhibiting the effect of the hypertension-causing enzyme ACE." (PMID 40837429, 2025). "Single nucleotide polymorphisms (SNPs) in the ACE gene have been studied in relation to hypertension, and regional differences in susceptibility have been revealed." (PMID 40370871, 2025). "This risk should be carefully considered when prescribing ACE inhibitors for hypertension in breastfeeding women, as ovulation can still occur during lactation, potentially leading to unintended pregnancy." (PMID 40507483, 2025). "Due to their large extensive use in pediatric and neonatal heart failure, wide therapeutic range and low risk of adverse effects, ACE-Is are increasingly replacing BB as first-line treatment for hypertension." (PMID 40260103, 2025). "As mentioned, ACE is an angiotensin-converting enzyme, and it has been used as a drug target to control hypertension and associated complications." (PMID 40725452, 2025). "3-hydroxyl-3-methylglutaryl-coenzyme A (HMG-CoA) reductase and angiotensin converting enzyme (ACE) are implicated in the pathogenesis of hyperlipidemia and hypertension, which are oxidative-stress linked conditions of public health importance." (PMID 40703712, 2025). "As a result, it is highly significant to develop food-based ACE inhibitors that can help reduce kidney damage caused by hypertension while minimizing side effects." (PMID 40284165, 2025). "During our study, the minor allele of the ACE gene rs4309 was identified as a risk factor for hypertension among older Japanese community-dwelling individuals." (PMID 40370871, 2025). "A key genetic feature is the ACE insertion/deletion (I/D) polymorphism in intron 16, which influences both hypertension and AD risk, with population‐specific effects." (PMID 40372199, 2025). "Beyond direct oxidative stress, previous studies have also demonstrated that lead exposure caused protein kinase C activation, NF-κB activation, and angiotensin-converting enzyme (ACE) activity as a possible means of increasing the risk for hypertension." (PMID 40427486, 2025). "The angiotensin-converting enzyme (ACE) is the enzyme that converts angiotensin I to angiotensin II, causing vasoconstriction, playing an important role in the pathogenesis of hypertension, diabetic nephropathy, and recently in DN." (PMID 39997711, 2025). "Polymorphisms of the ACE gene, particularly insertion/deletion types, can affect susceptibility to hypertension in children, although their direct impact on RAAS activity is still being investigated." (PMID 40806733, 2025). "Female sex, age > 50 years, and hypertension were associated with worse outcomes, and statins or ACE inhibitors with better outcomes." (PMID 39870668, 2025). "Higher plasma ACE activity is associated with the development of DN, arterial hypertension, LVH, and myocardial infarction." (PMID 40149592, 2025). "The ACE gene, a well-researched gene associated with hypertension, encodes an enzyme that converts angiotensin I into angiotensin II." (PMID 40004206, 2025). "The minor allele of the ACE gene rs4309 is a risk factor for hypertension in older Japanese community-dwelling individuals." (PMID 40370871, 2025). "Our study demonstrated that the minor allele of the ACE gene rs4309 is an independent risk factor for hypertension in older Japanese community-dwelling individuals." (PMID 40370871, 2025).
Hypertension (continued). "On the other hand, hypertension and diabetes were found to increase the risk of hospitalisation, while for medications to treat these conditions, i.e. metformin, ACE inhibitors, and ARB + RI, the results were inconclusive." (PMID 39923000, 2025). "Despite the availability of various angiotensin I-converting enzyme (ACE) inhibitor drugs, the mortality rate associated with hypertension continues to rise." (PMID 40278278, 2025). "The ACE gene polymorphisms rs7213516, rs7214530, and rs4290 - commonly observed in African Americans, a population with a higher risk of hypertension and reduced responsiveness to ACE inhibitors - have been associated with decreased ACE mRNA expression." (PMID 40370871, 2025). "Although synthetic ACE inhibitors, such as captopril, enalapril, and lisinopril, are effective in hypertension management, their long-term use is frequently associated with adverse side effects, including dry cough, angioedema, hyperkalemia, and hypotension." (PMID 41517150, 2025). "This study investigates the role of the ACE I/D polymorphism in Alzheimer's disease (AD) patients, particularly in relation to hypertension and its influence on brain volume." (PMID 40372199, 2025). "Both groups had comparable distributions of coronary artery disease risk factors, including diabetes mellitus, hypertension, and hyperlipidemia, as well as similar medication use profiles (e.g., aspirin, beta-blockers, ACE inhibitors)." (PMID 40075826, 2025). "ACE inhibitors and angiotensin receptor blockers are widely used in HFpEF patients to control the associated hypertension." (PMID 40124767, 2025). "Hypertension, a known risk factor for cardiovascular disease, can be treated with the administration of drugs inhibiting an enzyme known as Angiotensin I-Converting Enzyme (ACE)." (PMID 40007962, 2025). "The hypertension is usually associated with the hyperactivity of the renin, ACE or angiotensin receptor." (PMID 40430466, 2025). "In humans, enzymes that play a role in the prevention and development of MS include angiotensin converting enzyme (ACE-1) associated with hypertension, α-amylase associated with T2D, and lipase linked to the development of obesity." (PMID 39856950, 2025). "Hypertension is a major pathogenic contributor to cardiovascular diseases, primarily mediated through activation of the angiotensin-converting enzyme (ACE) system." (PMID 40868867, 2025). "The results showed an association between the ACE I/D genotype, under a recessive model, and the presence of hypertension in case groups." (PMID 41272596, 2025). "Located on the long arm of the chromosome 17 (17q23), ACE gene presents multiple polymorphisms, the most studied being ACE I/D because of its strong association with cardiovascular diseases, including hypertension." (PMID 41301901, 2025). "Effective treatment often requires the use of angiotensin-converting enzyme (ACE) inhibitors, angiotensin II receptor blockers (ARBs), and thiazide diuretics to manage concomitant diseases such as hypertension and cardiovascular risk in T2DM patients." (PMID 40988753, 2025). "CGA and caffeic acid have been reported as potential ACE inhibitory agents and other key enzymes linked to hypertension, with an inhibition percentage of less than 50% for both phenolic acids, compared to 80% for the positive control (captopril)." (PMID 40004104, 2025). "Predicted targets of the ACE-inhibitory peptides were identified and compared to known hypertension-associated genes." (PMID 40710492, 2025). "Previous studies have reported that NO-deficient hypertension is linked to left ventricular hypertrophy because it raises renin and testosterone levels, activates ACE, and increases the expression of ATI, which has a direct vasoconstrictive effect." (PMID 40137963, 2025).